EGFR (epidermal growth factor receptor)
Diseases named in the same sentence as EGFR in open-access papers (continued):
Sharing a sentence is not in itself a finding about the gene and the disease.
brain tumors (continued). "Molecular alterations assessed in brain tumors include IDH1/2 mutations, Histone H3F3A mutation, MGMT promoter methylation, TERT promoter methylation, EGFR amplification, ATRX retention or loss, and 1p/19q chromosomal co-deletion, for example." (PMID 37189838, 2023). "Recent reports have revealed the possibility of delivering anti-EGFR therapies to brain tumours through the invention of stem cell-delivered anti-EGFR nanobodies." (PMID 36071488, 2022). "Our data underline the potential of ZEGFR:03115-IR700 to accurately visualise EGFR-positive brain tumours and to destroy tumour cells post-conjugate irradiation turning an immunosuppressive tumour environment into an immune-vulnerable one." (PMID 35057796, 2022). "The fact that EGFR-amplified brain tumours are enriched with astrocyte-like cell states reflects the importance of maintaining ionic currents in these cells." (PMID 36497413, 2022). "Patients with EGFR 19del (18 patients) were more likely to have multiple BMs and smaller brain tumors with smaller peritumoral brain edema than those (31 patients) with wild-type EGFR (p = 0.024, p = 0.0016, and p = 0.0036, respectively)." (PMID 36457515, 2022). "IHC staining confirmed a high expression pattern of the brain tumor derived from A431 cells, which express high levels of EGFR, and a low expression pattern of the brain tumor derived from the TS895 cells that express low levels of EGFR." (PMID 35145836, 2022). "Our research is aimed at the development of radioligands conjugated with EGFR-specific single-stranded DNA aptamers for use in PET imaging for diagnostics of brain tumors which overexpress EGFR." (PMID 36615487, 2022). "The upregulation of TMEM43 in brain tumor cells accelerated brain tumor progression through the interaction of TMEM43 with CARD-containing MAGUK protein 3 (CARMA3) in the EGFR-induced NF-κB pathway." (PMID 35260078, 2022). "Previous studies indicated that TMEM43 facilitated brain tumor progression by mediating EGFR-induced NF-κB activation and promoting the phosphorylation of ERK." (PMID 35260078, 2022). "Consistence with these results, depletion of PFKP expression inhibited the growth of brain tumors in the group intracranially injected EGFR-expressing naïve LN229 cells." (PMID 36435833, 2022). "In summary, our findings demonstrate that Infinium EPIC Bead Chip analysis that is routinely applied in molecular brain tumor classification is a reliable technique for detecting EGFR amplifications compared with standard FISH analysis." (PMID 35453544, 2022). "Since the RNAi therapeutic is delivered to the brain tumor via the tumor vasculature, the knockdown of tumor EGFR has a self-limiting effect on the ultimate survival outcome." (PMID 35745855, 2022). "By contrast, in brain tumor, the hyperactive EGFR and its downstream signals activate Aurora B and PKM2 to facilitate cytokinesis." (PMID 36198360, 2022). "Cetuximab (CET) is an anti-epidermal growth factor receptor (EGFR) monoclonal antibody developed for brain tumor targeting because CET specifically binds with high affinity to EGFR." (PMID 36145722, 2022). "U251 was selected to establish the orthotopic brain tumor model in mice due to its modest EGFR expression in tumors and to test the feasibility of detecting HGG with panitumumab-IRDye800 in vivo." (PMID 33707521, 2021). "Overall, the present study contributes to the existing literature by showing that e-liquid exposure can boost cell proliferation and malignancy of brain tumor via the increase in EGFR phosphorylation." (PMID 34495991, 2021). "The results indicated that GFAP-IML CTCs isolation system, combined with an EGFR immunofluorescence assay of antitumor marker, can serve as a brand-new method for the identification of CTCs for brain tumors." (PMID 33208163, 2020). "Targeting the EGFR signal transduction pathway in brain tumors faces the issue of rapid adaptation through activation of alternative signaling pathways." (PMID 32111026, 2020).
brain tumors (continued). "This approach has also been used for delivery of small interfering RNA (siRNA) against epithelial growth factor receptor (EGFR) and demonstrated the knock-down of EGFR expression and increased survival of mice implanted intracranially with brain tumors." (PMID 32581676, 2020). "Given the importance of EGFR and its isoforms in brain tumors, several agents have undergone clinical trials in an attempt to target EGFR (i.e., lapatinib, gefitinib) but outcomes have been largely disappointing." (PMID 32849207, 2020). "Flow cytometry was used to demonstrate a stronger reaction with EMab-17 LN229/EGFR than with endogenous EGFR-expressing LN229 brain tumor cells, which indicated that EMab-17 is EGFR-specific." (PMID 32218834, 2020). "The OSMR (receptor for the cytokine Oncostatin M) is a regulator of brain tumor stem cells (BTSC) proliferation by mediating EGFR phosphorylation." (PMID 32725165, 2020). "Another tumor-specific factor implicated in pro-tumorigenic tumor–tumor crosstalk via MV is the truncated oncogenic form of the epidermal growth factor receptor (EGFR), EGFRvIII, which is commonly expressed in aggressive brain tumor cells." (PMID 32731639, 2020). "In this study, we investigate the role of 6PGD phosphorylation in EGFR-promoted tumor growth and radiation resistance, highlighting the fundamental role of Fyn-dependent 6PGD phosphorylation in brain tumor development." (PMID 30824700, 2019). "In present study, we observe 6PGD phosphorylation for the first time, which responds to EGFR signaling and plays an important role in EGFR-promoted brain tumor development." (PMID 30824700, 2019). "Two of them received the surgery after they started taking EGFR-TKIs for better local control because of large brain tumors (5.6 cm and 6.4 cm in diameter, respectively)." (PMID 31655564, 2019). "The EGFR, also known as ErbB1/Her1, is a key factor for brain tumors as it supports the proliferation and stemness of neural progenitor cells from which these tumors originate." (PMID 31861467, 2019). "Experimental studies have demonstrated that both the extracellular vasculature or microenvironment and intracellular molecular network (e.g., epidermal growth factor receptor (EGFR) signaling pathway) are important for brain tumor growth." (PMID 31074391, 2019). "In conclusion, the ZEGFR:03115–IR700DX showed specific uptake in vitro and enabled imaging of EGFR expression in the orthotopic brain tumor model." (PMID 29313975, 2018). "Subsequent flow cytometry demonstrated that EMab-51 reacted with LN229/EGFR more strongly than with endogenous EGFR-expressing LN229 brain tumor cells." (PMID 28891752, 2017). "Copy number analyses of the six brain tumours using both sWGS and Hi-C confirmed amplifications of the EGFR region on chromosome 7 in GB176, GB180 and GB182, as suggested by the Hi-C interaction data." (PMID 28655341, 2017). "We were able to show a response of the brain tumours to drug treatment as evidenced by a reduction of phosphorylated EGFR in the majority of samples following treatment with dacomitinib." (PMID 28394918, 2017). "According to the T2 relaxation time and mean intensity of the MR images, EGFRhigh U-251 cells were distinguished from EGFRlow U-87MG cells in vitro, which suggests the potential use of this system in noninvasive EGFR status detection for brain tumors." (PMID 29166921, 2017). "High probe uptake by brain tumors in mice, the possibility of conjugation with anti-epidermal growth factor receptor (EGFR), and a high tumor-to-background ratio are reported." (PMID 27800481, 2016). "Here, we have reported that minicell encapsulation of Dox and targeting to EGFR permitted accumulation in canine brain tumors and demonstrated therapeutic efficacy." (PMID 27050167, 2016). "There are studies showing that combining rapamycin, an mTOR inhibitor, with an EGFR inhibitor improves the clinical outcome in a small number of patients with recurrent GBM brain tumor." (PMID 27788487, 2016).
brain tumors (continued). "Frequency and/or type of mutations in genes encoding isocitrate dehydrogenase 1 (IDH1), isocitrate dehydrogenase 2 (IDH2), and epidermal growth factor receptor (EGFR) vary between histological types of primary brain tumors." (PMID 27454254, 2016). "Brain tumours developed upon injection of Ras/EGFR/SrciNPCs showed a nodular growth with perivascular spread but not much diffuse parenchymal invasion was observed." (PMID 26899176, 2016). "MLPA analysis did not reveal any differences between DK-MG lines, other than EGFRvIII, with both lines having normal number of wild-type EGFR copies, hemizygous PTEN and NFkBIA, and CDKN2A deleted; all mutations reminiscent of brain tumors." (PMID 27004406, 2016). "Overexpression of EGFR, over-expression of drug efflux pumps, and extensive invasion into normal brain and peritumoral edema are also observed in dog brain tumors." (PMID 27050167, 2016). "While the majority of brain tumors show an overexpressed or mutant EGFR, TKI remain inefficient and even patients that show some response eventually recur as a result of acquired resistance." (PMID 25978031, 2015). "Treatment of U87MG brain tumours with nimotuzumab and radiation has also shown enhanced inhibition of EGFR-signalling activation." (PMID 25918252, 2015). "We showed that CSF ctDNA is more representative of brain tumour genomic alterations than plasma and putative actionable gene mutations and CNA (that is, EGFR, PTEN, ESR1, IDH1, ERBB2, FGFR2) can be identified." (PMID 26554728, 2015). "Brain tumors can also be selectively targeted by bionanocapsules conjugated with anti-human EGFR antibody that recognizes EGFRvIII known to be overexpressed in high grade brain tumors like glioblastoma multiforme." (PMID 25866775, 2015). "EGFR/ErbB2 TK inhibitors were well tolerated, but more importantly, showed limited clinical response in brain tumor patients including patients with medulloblastoma (NCT00095940; NCT00077454)." (PMID 26496080, 2015). "Developing inhibitors to the proteins identified during this study will provide alternatives to patients with recurrent brain tumors that are refractory to EGFR therapy." (PMID 25978031, 2015). "EGFR has been the focus of many brain tumor studies and it is noteworthy that expression of wild-type or constitutively active mutant EGFR is rarely oncogenic as a single lesion, whereas expression of PDGFR ligands can induce tumors as a single driving event." (PMID 25380967, 2014). "The Notch signaling pathway is increasingly recognized as a central player in brain tumor formation beyond targeting the “usual suspects” such as EGFR and PI3K." (PMID 25601901, 2014). "HIP1 gene encodes for Huntingtin interacting protein 1 (HIP1) that is predominantly expressed in brain and is proposed as a novel brain tumor marker that interacts with EGFR." (PMID 24628925, 2014). "This suggests that radiation-based therapy reinforces the EGFR oncogene addiction of neural cancer stem cells, adding a rationale for combining anti-EGFR antibodies and radiotherapy to treat brain tumors." (PMID 23637683, 2013). "In brain tumors, there is evidence suggesting that EGFR signaling plays a role in tumor initiation and progression." (PMID 24381541, 2013). "We performed a copy number variation (CNV) assay to assess the EGFR amplification status in 69 primary GBM (here defined as brain tumors, BT) and in corresponding neurospheres (here defined as NS), cultured in the presence of EGF and bFGF." (PMID 24330732, 2013).
brain tumors (continued). "Significantly, virus-based liposome delivery also facilitated targeted binding of Quantum dots to cytosolic Epidermal Growth Factor Receptor within cultured cells, focal to the early detection and characterization of malignant brain tumors." (PMID 22339792, 2012). "This work presents a novel multi-scale agent-based brain tumor model encompassing an EGFR signaling pathway together with a related cell-cycle, an angiogenesis module and TKI treatment." (PMID 22935054, 2012). "BNCs displaying anti-human EGFR monoclonal antibodies were delivered successfully to glioma cells in a mouse model of brain tumors." (PMID 23304519, 2012). "It has been suggested that the molecular mechanisms for EGFR activation are autocrine regulation or gene amplification in other organ malignancies such as breast or brain tumors." (PMID 21197106, 2011). "Noteworthy, overexpression of the truncated EGFR in U-87MG.EGFRvIII is comparable to levels seen in primary brain tumors." (PMID 20657384, 2010). "Shh and EGFR signaling pathways, each of which can mediate brain tumor generation and/or malignancy, were identified as the most prominently up- and down- regulated oncogenic pathways, respectively, common to GBM and GL26 exposed to T cells in vivo." (PMID 20539758, 2010). "EGFR is the main oncogene identified in brain tumours, but its prognostic value is controversial, although a fairly strong correlation with OS was observed in the present study." (PMID 18506188, 2008). "Primary GBM used to be the most common and developed in patients with no prior record of brain tumors, with EGFR overexpression, PTN (MMC I) mutation, and CDKN2A (p16) deletion." (PMID 39202515, 2024). "Likewise, immuno-liposomes with the anti-EGFR antibody IMC-C225 have improved the delivery of chemotherapeutic agents to brain tumor cells." (PMID 39204177, 2024). "Following systemic administration, the CRISPR/Cas12a system demonstrated promising brain tumor accumulation that led to extensive EGFR and PLK1 gene editing in both U87MG and patient‐derived GSC xenograft mouse models with negligible off‐target gene editing detected through NGS." (PMID 38943253, 2024). "Overall, these results are consistent with the notion that MES-GSC-initiated brain tumours mount multiple vascular growth responses, either through vasectasia driven by EGFR (EGFR-EVs) or through angiogenesis, the latter dependent, at least in part, on the VEGF pathway." (PMID 38570528, 2024). "Indeed, in this GBM zebrafish model, the activation of the EGFR/RAS/ERK/AKT pathway through the zic4 enhancer induces brain tumor development with a mesenchymal GBM signature." (PMID 36982845, 2023). "Another gene that is overexpressed in pediatric brain tumors is EGFR." (PMID 37891817, 2023). "However, several ADC therapies have been developed for brain tumors, and clinical trials with Depatux-M targeted at EGFR generated some long-term responses in patients with recurrent, EGFR-amplified GBM." (PMID 35217608, 2022). "Prior to IV administration in EGFR expressing brain-tumor-bearing rats, the two vials were mixed." (PMID 35745855, 2022). "The EGFR has a pro-angiogenic effect in brain tumors [1063]." (PMID 35745855, 2022). "After demonstrating that ZEGFR:03115-IR700 cell uptake enables imaging of EGFR expression in an orthotopic brain tumour model (U87-MGvIII), our proof-of-concept in vivo PIT study also showed the conjugate’s therapeutic efficacy in subcutaneous glioma xenografts." (PMID 35057796, 2022).
brain tumors (continued). "Thus, the in vitro cell study showed that e-liquid activates EGFR signaling and influences the growth of brain tumor cells via pERK activation while animal xenograft study showed that e-liquid promotes accelerated cancer growth which leads to poor prognosis." (PMID 34495991, 2021). "Amplification of EGFR is commonly seen in brain tumors, making it a possible target for therapies." (PMID 34298788, 2021). "Besides, the transport of the epidermal growth factor receptor via EVs from bladder, colorectal, and brain tumor cells can also activate the PI3K-Akt pathway." (PMID 34186243, 2021). "Thus, the present study was conducted to reveal that e-liquid mixture can boost proliferation and malignancy of brain tumor cells by increasing EGFR phosphorylation, resulting in poor prognosis in an orthotopic animal model." (PMID 34495991, 2021). "Thus, we conclude that e-liquid promotes brain tumor cell proliferation via the activation of the EGFR-pERK signaling pathway." (PMID 34495991, 2021). "From the obtained data, we concluded that elevated activation level of EGFR stimulates the increase in pERK expression related downstream signaling pathway which may be responsible in promoting malignancy of brain tumor in the orthotopic mouse models." (PMID 34495991, 2021). "We were able to establish the relation between e-liquid and EGFR expression in brain tumor." (PMID 34495991, 2021). "All together, these results could partially explain the resistance of GBMs to treatments targeting EGFR; in addition, our data further support the fundamental relevance of S1P signaling as a therapeutic target in these brain tumors." (PMID 34201962, 2021). "In the future, SA-based PAMAM dendrimers co-loaded with medicinal drugs that target the specific proteins of brain tumors [e.g., integrins and epidermal growth factor receptor (EGFR)], have the potential to improve drug retention within tumors and to augment the medicinal effects." (PMID 32391334, 2020). "Notably, the intensity of membrane EGFR staining was stronger in metastatic brain tumors than in primary lung tumors (representative images shown)." (PMID 33042262, 2020). "Inhibition of EGFR degradation also contributes to malignancy in brain tumors." (PMID 31861467, 2019). "Interestingly, most genetic alterations harbored by brain tumors including alterations of EGFR, NF1, PTEN and AKT, are known to be involved in autophagy regulation." (PMID 29692710, 2018). "Similarly in dogs, there is significantly greater expression of EGFR in GBMs compared to other canine inter-cranial brain tumours that have been documented." (PMID 29069805, 2017). "No BRAF exon 15 and EGFR exons 3 and 7 mutations were identified in 54 and 31 assessed primary brain tumors, respectively." (PMID 27454254, 2016). "Specifically, this study sought to evaluate the safety and efficacy of EGFR targeted, doxorubicin loaded minicells (designated EGFRminicellsDox) to deliver doxorubicin to spontaneous brain tumors in 17 companion dogs; a comparative oncology model of human brain cancers." (PMID 27050167, 2016). "This antibody has been used to reduce EGFR-mediated self-renewal in human brain tumor stem cells." (PMID 23620784, 2013). "When comparing brain tumor cryosections gray scale intensities for EGFR-IL and hIgG-IL, an increase of 3.39 fold versus 1,95-fold change could be observed above the background fluorescence of the tumor tissue." (PMID 24175095, 2013). "EGFR was chosen as a candidate target protein because its over-expression and up-regulation is recognized as a significant step in the pathogenesis and progression of a wide variety of cancers, including tumors of the brain." (PMID 22339792, 2012). "Pardridge and his collaborators have applied immunoliposomes containing a short hairpin RNA (shRNA) expression vector against the epidermal growth factor receptor (EGFR) to suppress brain tumour proliferation with a single intravenous injection in adult rats with intracranial brain tumours." (PMID 21304523, 2011).